GDF15 (growth differentiation factor 15)
Diseases named in the same sentence as GDF15 in open-access papers (continued):
Sharing a sentence is not in itself a finding about the gene and the disease.
idiopathic pulmonary fibrosis (13 papers, 2019 to 2026). Idiopathic pulmonary fibrosis (IPF) is a nonneoplastic pulmonary disease that is characterized by the formation of scar tissue within the lungs in the absence of any known cause. "In idiopathic pulmonary fibrosis (IPF), GDF15 is identified as a novel cell-specific marker of epithelial injury and a novel biomarker of IPF severity." (PMID 34179129, 2021).
iron overload (13 papers, 2014 to 2025). "Iron overload in thalassemia syndromes was also found to be associated with growth differentiation factor 15 (GDF15) overexpression related to an expanded erythroid compartment and the inhibition of hepcidin expression." (PMID 34575839, 2021). "Herein, we describe the kinetics of hepcidin, ERFE, and GDF15 levels in a patient diagnosed with megaloblastic anemia associated with iron overload." (PMID 34538261, 2021). "GDF-15 is inversely associated with hepcidin, a key regulator in systemic iron homeostasis in mammals, expediting intestinal iron absorption leading to iron overload." (PMID 35251002, 2022). "We hypothesized that ineffective erythropoiesis was associated with high levels of ERFE and GDF15 at the time of diagnosis, possibly associated with suppressed hepcidin, thus explaining the iron overload." (PMID 34538261, 2021). "GDF-15 plays a key role in iron metabolism by suppressing hepcidin expression, thereby promoting increased intestinal iron absorption despite systemic iron overload." (PMID 41517557, 2025). "GDF-15 also plays a crucial role in the inhibition of hepcidin secretion and subsequent tissue iron overload observed in patients with disorders characterized by inadequate erythropoiesis." (PMID 38203404, 2023). "The associations of GDF15 and EPO levels with erythropoiesis markers and iron overload support their potential value in early identification of NTDT patients with a risk of EMH." (PMID 30834265, 2019). "In the iron overload group, high levels of iron, identified by the high concentration of serum ferritin, overlapped the elevation of GDF-15 levels, possibly leading to higher hepcidin concentration." (PMID 29673144, 2018). "Also, the diagnostic performance of GDF-15 as a marker of inflammation in CKD was comparable to CRP and better than ferritin that is mostly elevated by iron overload associating CKD, qualifying GDF-15 as a surrogate marker of inflammatory status in CKD." (PMID 37649102, 2023). "Splenectomy, which is associated with an increase of sTfR, may adversely affect the degree of ineffective erythropoiesis, thus modifying GDF15 levels and thus far unknown “erythroid regulators” which increase the risk for EMH and iron overload." (PMID 30834265, 2019). "The aim of this study in NTDT patients was to establish relationships between the erythropoiesis biomarkers (GDF15, EPO, sTfR, and ERFE) and iron overload markers (SF, LIC, and hepcidin) with the severity as well as complications of EMH." (PMID 30834265, 2019). "On the other hand, GDF-15 has been shown to inhibit hepcidin expression and then increase iron absorption regardless of iron overload in patients with beta-thalassemia." (PMID 38883134, 2024). "Those with iron overload had higher GDF15 levels compared with non-iron overload patients." (PMID 39139819, 2024).
lung adenocarcinoma (13 papers, 2013 to 2025). A carcinoma that arises from the lung and is characterized by the presence of malignant glandular epithelial cells. "Enhanced GDF-15 expression also reduces the number and sites of local and distal metastases in vivo compared to control group in lung adenocarcinoma." (PMID 35963873, 2022). "GDF15 could inhibit the growth and bone metastasis of lung adenocarcinoma A549 cells through TGF‐β/Smad signaling pathway." (PMID 38230211, 2024). "Through our analysis and prediction, GDF15 may be also related to platinum resistance of lung adenocarcinoma, which needs further verification by subsequent experiments." (PMID 36506331, 2022). "For instance, in lung adenocarcinoma, TK1 overexpression has been shown to promote tumor growth and metastasis through Rho GTPase activation and downstream regulation of GDF15." (PMID 40564887, 2025).
peripheral artery disease (13 papers, 2017 to 2025). "Characteristics of 439 outpatients with peripheral arterial disease according to tertiles of GDF-15." (PMID 39780955, 2024). "It was shown that serum blood level of GDF15 is increased in patients with peripheral artery diseases; their protective role against atherogenesis was described." (PMID 36140167, 2022). "Patients with higher circulating GDF-15 were nonsignificantly older, had a lower body mass index (24 vs. 27 kg/m2, P = 0.04), and a higher prevalence of peripheral artery disease (33% vs. 0%, P = 0.04) compared to patients with lower circulating GDF-15." (PMID 37008733, 2023). "A study of elderly Caucasian individuals aged over 65 years without a history of cerebrovascular, cardiovascular, or peripheral artery disease found a link between GDF‐15 and markers of subclinical atherosclerosis such as coronary artery calcium scores and ankle‐brachial index." (PMID 40495286, 2025). "In this study, GDF-15 was found to be a significant and independent factor affecting coronary artery calcification in individuals over 65 years of age without a history of cerebrovascular, cardiovascular, or peripheral artery disease." (PMID 37548881, 2024). "We aimed to evaluate how the relative plasma concentrations of NT-proBNP and GDF-15 obtained with the PEA correlate with the absolute plasma concentrations obtained with a conventional assay in individuals with and without verified manifest peripheral arterial disease (PAD)." (PMID 36694116, 2023).
Alzheimer disease (12 papers, 2016 to 2025). A progressive, neurodegenerative disease characterized by loss of function and death of nerve cells in several areas of the brain leading to loss of cognitive function such as memory and language. "UPF1 has been identified as a RBP binding to circRPPH1 influencing tumor process, and recruited by circLPAR1 to modulating GDF-15 mRNA stability involved in Alzheimer’s disease." (PMID 39300342, 2024). "Therefore, we aimed to study peripheral levels of GDF-15 incognitive impairment no dementia (CIND) or Alzheimer disease (AD) subjects assessed for CeVD using a case–control cohort design, with cases recruited from memory clinics and controls from memory clinics and the community." (PMID 27537582, 2016).
autoimmune disease (12 papers, 2020 to 2026). A disorder resulting from loss of function or tissue destruction of an organ or multiple organs, arising from humoral or cellular immune responses of the individual to their own tissue constituents. "In certain autoimmune diseases, high values of GDF15 are observed, which favors the induction of GDF15 in inflammatory conditions." (PMID 38699700, 2024). "We also excluded participants with hypoglycaemic, antihypertensive, and lipid-lowering drugs and some disease states, such as CVD, autoimmune diseases, and cancers, to avoid the impact on the detection of GDF-15 and adiponectin." (PMID 37152921, 2023). "GDF15 was reported to be a biomarker of autoimmune diseases, such as autoimmune hepatitis." (PMID 41303556, 2025). "In conclusion, GDF15 levels are increased in patients with PAI compared with healthy controls and correlate with age and the duration of autoimmune disease." (PMID 41828483, 2026). "For another autoimmune disease, Type 1 diabetes (T1D), elevated GDF-15 activity was described in beta cells, and GDF-15 was proposed as a biomarker for T1D." (PMID 32508832, 2020).
lymph node metastasis (12 papers, 2011 to 2025). "Elevated plasma level of GDF-15 is associated with aggressive disease and lymph node metastasis in endometrial carcinoma." (PMID 30645608, 2019). "We conclude that elevated levels of plasma GDF-15 is associated with an aggressive clinical phenotype and lymph node metastasis in endometrial carcinomas." (PMID 30645608, 2019). "GDF15 was implicated in multiple cancer types and correlates with lymph node metastases in endometrial cancer and overexpression of IGF-2 or PTGS2 mRNAs in breast tumors associated with greater mortality and increased metastatic potential." (PMID 26910917, 2016). "Immunohistochemical analysis of GDF15 expression in CRC has also been associated with lymph node metastasis." (PMID 21468045, 2011). "In endometrial cancer, high plasma GDF-15 was, again, an independent predictor of poor disease-specific and short recurrence-free survival and was significantly associated with high tumor grade and lymph node metastasis (all p ≤ 0.001)." (PMID 32508832, 2020). "Additionally, high serum GDF15 increased the risk of lymph node metastasis to lateral neck." (PMID 36046792, 2022). "Furthermore, in the merged cohort of 495 patients with lymph node status (also described in materials and cut-off value of 1418 ng/L), high plasma level of GDF-15 was significantly associated with lymph node metastases (OR = 2.64; 95% CI 1.52–4.61) in univariate analysis." (PMID 30645608, 2019). "Collectively, high levels of GDF-15 are positively linked to poor prognosis in patients with NSCLC, manifesting as shorter overall survival, higher risk of lymph node metastasis, and higher recurrence rates." (PMID 40144214, 2025). "In an opposite manner to TXNIP, GDF15 showed a significantly positive correlation with clinical stage and lymph node metastasis in CRC specimens." (PMID 39103698, 2024). "The clinical value of plasma GDF-15 for prediction of lymph node metastases, prognostication and as a marker of recurrent disease, however, needs to be validated in larger patient cohorts and in clinical trials prior to potential implementation in the clinic." (PMID 30645608, 2019). "Our objective was to explore the applicability of plasma growth differentiation factor 15 (GDF-15) as a marker for recurrent disease, as well as a marker for poor prognosis and lymph node metastases." (PMID 30645608, 2019). "High plasma level GDF-15 independently predicts recurrent disease (OR = 3.14; 95% CI 2.10–4.76) and lymph node metastases (OR = 2.64; 95% CI 1.52–4.61)." (PMID 30645608, 2019). "The elevated GDF15 expression showed a significant correlation with lymph node metastasis (P < 0.05) and distant metastasis (P < 0.05)." (PMID 26497212, 2016). "Our previous study identified GDF15 as the potential biomarker of lymph node metastasis in CRC using LC-MS/MS-based label-free quantitative proteomics approach." (PMID 26497212, 2016). "GDF-15 could therefore be helpful as an indicator of lymph node metastases and when selecting women for lymphadenectomy." (PMID 30645608, 2019). "Then, we analyzed the association between plasma GDF15 level and clinical characterizations in CRC patients, which showed a significant correlation between high plasma GDF15 levels and differentiation, lymph node metastasis, distant metastasis and TNM grade (P < 0.01)." (PMID 26497212, 2016). "Patients with moderate to high intensity of immunoreactivity of GDF15 in the lymph node metastases did not have any higher risk of recurrence compared with patients with no to low intensity of GDF15 (P=0.08)." (PMID 21468045, 2011). "In 42 out of 100 curatively treated patients with stage III disease, immunohistochemical staining for GDF15 could be assessed in lymph node metastases." (PMID 21468045, 2011). "Serum levels of GDF15 were significant higher in DGC patients as compared with healthy individuals and chronic gastritis patients, and positively correlated with wall invasion and lymph node metastasis." (PMID 26892343, 2016).
oral squamous cell carcinoma (12 papers, 2013 to 2026). "Another, growth differentiation factor 15 (GDF15) is involved in the pathogenesis of oral squamous cell carcinoma (OSCC)." (PMID 34980250, 2022). "Among patients with oral squamous cell carcinoma, those with elevated GDF-15 showed significantly shorter survival (p = 0.031)." (PMID 32508832, 2020). "However, oxidative stress, a well-known source of DNA damage, induced by radiation highly increased the GDF15 levels in oral squamous cell carcinoma cells." (PMID 38247838, 2024). "In addition, GDF15 overexpression accelerated the growth and progression of oral squamous cell carcinoma, whereas GDF15 knockdown in malignant gliomas decreased cell proliferation in vitro and carcinogenesis in vivo." (PMID 36698183, 2023). "For example, GDF15 knockdown in malignant gliomas reduced cell proliferation in vitro and tumorigenesis in vivo, while GDF15 overexpression promoted tumorigenesis and progression in oral squamous cell carcinoma." (PMID 29636108, 2018). "Herein, we performed single-cell RNA-sequencing on oral squamous cell carcinoma (OSCC) samples before and after ICB-based therapy to explore the context-dependent functions of GDF15 across distinct cellular subsets." (PMID 41824793, 2026). "In immortalized oral mucosal and oral squamous cell carcinoma (OSCC) cell lines, GDF-15 overexpression also resulted in increased phosphorylation of Akt and ERK1/2 and significant induction of cell proliferation, migration, invasion, and colony formation." (PMID 32508832, 2020).
dilated cardiomyopathy (11 papers, 2014 to 2025). Cardiomyopathy which is characterized by dilation and contractile dysfunction of the left and right ventricles. "GDF-15 has also been associated with fibrosis in diseases of other organ systems such as dilated cardiomyopathy, systemic sclerosis, and chronic liver disease." (PMID 32089755, 2020). "We also examined GDF15 expression in a murine model of dilated cardiomyopathy where cardiac-specific ablation of Yme1l (cYKO) in mice induces mitochondrial fragmentation and altered cardiac metabolism." (PMID 39312445, 2024). "The release of GDF-15 increases in response to cardiomyocyte tissue injury such as in the context of LV hypertrophy and dilated cardiomyopathy." (PMID 36001499, 2022). "sST2 independently predicted all-cause mortality in non-ischemic, dilated cardiomyopathy during a follow-up of 7 years, but it was inferior to growth differentiation factor-15 (GDF-15) for the prediction of fatal arrhythmic events in this patient population." (PMID 33415128, 2020). "In patients with end stage heart failure, the majority of whom had dilated cardiomyopathy, GDF15 levels were markedly elevated relative to healthy controls; however, GDF15 expression could not be detected in myocardial biopsies from the same participants by RT-PCR or by immunohistochemistry." (PMID 32310257, 2020).
esophageal squamous cell carcinoma (11 papers, 2016 to 2025). Esophageal squamous cell carcinoma (ESCC) is a type of esophageal carcinoma (EC) that can affect any part of the esophagus, but is usually located in the upper or middle third. "GDF-15 was proposed to promote esophageal squamous cell carcinoma progression via the TGF-βRII signaling pathway." (PMID 38254638, 2023). "For examples, expression of NAG1/GDF15 in esophageal squamous cell carcinomas was significantly correlated with several malignant phenotypes including vessel invasion and lynph node metastasis." (PMID 26910917, 2016). "Furthermore, GDF15 promoted the progression of Esophageal Squamous Cell Carcinoma through the activation of TGFBR2." (PMID 36698183, 2023). "Beyond its role in EndMT, GDF15 promotes AKT phosphorylation in a TGFBR2-dependent manner, hence increasing the resistance of esophageal squamous cell carcinoma cells to low-dose cisplatin." (PMID 41502509, 2025).
glaucoma (11 papers, 2020 to 2025). Increased pressure in the eyeball due to obstruction of the outflow of aqueous humor. "AH was obtained from the initial peripheral paracentesis for the planned glaucoma surgery, and GDF15 levels were quantified with enzyme-linked immunosorbent assay by an investigator masked to clinical information." (PMID 32983624, 2020). "The purpose of this study was to determine whether changes in the AH GDF15 levels were associated with intraocular pressure (IOP) changes in eyes undergoing glaucoma surgery." (PMID 33520124, 2021). "To explore this possibility, we performed a prospective, longitudinal pilot study to determine whether changes in AH GDF15 levels over a follow-up period of approximately six months are associated with IOP changes in eyes undergoing glaucoma surgery." (PMID 33520124, 2021). "Growth Differentiation Factor 15 (GDF15) was previously identified as a molecular marker of retinal ganglion cell stress in rodent models of glaucoma and was elevated in the aqueous humor (AH) of patients with primary open-angle glaucoma as a possible risk factor for glaucoma progression." (PMID 33520124, 2021). "Studies included in this review assessed GDF15 in the context of biomarkers for primary open angle glaucoma and pseudoexfoliative glaucoma, showing elevated levels in both diseases." (PMID 39737171, 2024). "In this relatively large cohort of POAG patients, the AH GDF15 levels were robustly elevated (by 7.4-fold) relative to the respective age- and gender-matched non-glaucoma cataract patient subgroup." (PMID 35160195, 2022). "GDF15 is a peptide hormone, its levels are known to be elevated under tissue injury, inflammation, and pathological conditions, including glaucoma." (PMID 35566463, 2022). "This study reveals a significant and marked elevation of GDF15 levels in the AH of POAG patients compared to non-glaucoma cataract control patients." (PMID 35160195, 2022). "This study reveals increased levels of GDF15 in both the AH and serum of POAG patients compared to age- and gender-matched non-glaucoma cataract patients, suggesting a strong association between elevated levels of GDF15 and POAG." (PMID 35160195, 2022). "Our study population was quite large, included NTG as well as HTG patients, and used linear regression models for detailed analysis of the relation between plasma GDF-15 concentration and glaucoma." (PMID 34048486, 2021). "Given this possible role of IOP fluctuation in glaucoma progression, especially for patients who show progression despite having IOPs near goal, the ability to use a molecular marker such as GDF15 as a marker of long-term IOP fluctuation is highly desirable." (PMID 33520124, 2021). "These future studies are essential before we can fully understand the translational possibilities of GDF15 as a molecular marker for glaucoma." (PMID 32983624, 2020). "To explore a plausible relationship between the levels of AH GDF15 and disease severity of glaucoma, we sub-classified glaucoma patients from the smaller cohort described above into mild (n = 10), moderate (n = 8), and severe (n = 20) POAG subgroups, based on the ICD-10 coding of each patient." (PMID 35160195, 2022). "This study provides proof of concept that GDF15, a molecular marker of retinal ganglion stress that was initially identified in rodent models, may have clinical utility as a measure of glaucoma severity not only in POAG but also in PXG." (PMID 32983624, 2020). "In addition, we aimed to determine whether plasma GDF-15 levels would help to identify glaucoma patients that have distinct mitochondrial dysfunction." (PMID 34048486, 2021). "Precise tracking of the biomarker Growth/Differentiation Factor 15 (GDF15) aids in the correct diagnosis and assessment of glaucoma." (PMID 40391083, 2025). "This platform utilized APT2TM aptamers to detect growth differentiation factor-15 (GDF15), a biomarker of glaucoma and potentially aging, and achieved an exceptionally low LOD of 5–6 pg/mL." (PMID 40277546, 2025).